IL17A (interleukin 17A)
Diseases named in the same sentence as IL17A in open-access papers (continued):
Sharing a sentence is not in itself a finding about the gene and the disease.
infection (continued). "After infection with <100 CFU, the mycobacterial burdens in IL-17A−/− mice were slightly but not significantly higher than those in C57BL/6 wildtype animals (left), corroborating previous findings showing that IL-17A contributes to containment of a low-dose Mtb infection to only a minor degree." (PMID 36139450, 2022). "Moreover, the maternal peripheral level of IL-17A and the placental and neonate IFN-γ levels were not significantly different due to the infection." (PMID 33422078, 2021). "While in IL-23p19−/− mice the protective effect was reduced, protection after vaccination was maintained in IL-17A−/− animals for the course of infection of 6 weeks, indicating that after vaccination with H1-DDA/TDB early protection against Mtb is—although dependent on IL-23—not mediated by IL-17A." (PMID 34351501, 2021). "We observed that regardless of the infection state in SFB colonized eSPF mice, within small intestinal LPLs nearly 100% of IL-17A+IL-22- cells expressed CD44+ and lacked CD62L expression with around 70% of them expressing CCR6, which is in contrast to IL-17A-IL-22- cells." (PMID 34566952, 2021). "Interestingly, IL-17A selectively blocked IFN-α2 production during CHIKV, but not West Nile virus (WNV) or Zika virus (ZIKV), infections." (PMID 33304351, 2020). "The levels of IL-17A produced by PBMC in response to antigen varied across the duration of the experiment, but no pattern in relation to infection could be established." (PMID 32487248, 2020). "In vivo, IL-17A and IL-6 are upregulated in early-stage MAP-infected lesions (Grade 1), but not in late infection/clinical Johne's disease lesions, suggesting that Th17 responses to MAP are subject to the same T cell exhaustion that occurs with Th1-like cells in late clinical JD." (PMID 32258066, 2020). "Interestingly, Beijing-1585 infection also showed a lack of induction, or even reduced expression of inflammatory cytokines IFN-γ, IL-17a and TNF-α compared to H37Rv as early as 3 dpi." (PMID 31882653, 2019). "Interestingly, this expression kinetics of IL-17A was also observed with PRU ROP16-I infection (not shown), which suggests an involvement of ROP16 in the active suppression of IL-17A." (PMID 30901349, 2019). "Infection did not affect the percentages of CD4+ T cells positive for interleukin-4 (IL-4) or the activation marker CD69; however, it increased percentages of IL-17A+ CD4+ T cells by 4.0-fold." (PMID 28442605, 2017). "The larger lesions observed in μMT mice were associated with approximately 10-fold greater numbers of bacteria recovered from the lesions 3 d after infection (p < 0.05), as well as higher levels of the inflammatory chemokine CXCL-1 (p < 0.01), but not IL-17A (p = 0.15)." (PMID 26828524, 2016). "Additionally, while IL-17A levels in bronchioaveolar lavage fluid (BALF) are not different between mice infected with RV and RSV, mice infected with RV were shown to produce higher BALF levels of neutrophils detected than those with RSV in early infection." (PMID 38410509, 2024). "Cytokine signaling of IL-1β, IL-23, IL-17A, CCL7, CXCL10, TRAIL, CD40L, and BAFF provides protection against acute WNV infection in mice; IL-10 and IL-22 aid in WNV pathogenicity; IL-6 and IL-12 had no apparent effect during infection; and CCL2, TNF-α, and FasL roles remain elusive." (PMID 36992514, 2023). "In the mutant strain infection, we noted that Th17-related cytokines (IL-17A, IL-22) and neutrophil-related chemokines (CCL2, CCL3, CXCL1, CXCL2) are significantly reduced at the early stage of infection, which might be related to the absence of melanin and defects in growth and germination." (PMID 35696422, 2022). "While IFN-γ was not significantly increased in WT animals following infection, we did observe an increase in the secretion of this cytokine in IL-17A KO animals, suggesting a compensatory mechanism requiring more robust IFN-γ responses in the absence of IL-17A." (PMID 34240122, 2021).
infection (continued). "Infection of developing B cells in the bone marrow contributes to the maintenance of long-term, but not peak, MHV68 latent reservoir, a process that may be independent of IL-17A signaling." (PMID 33824206, 2021). "However, the importance of IL-17A and IFN-γ could not be denied on the basis of this result as levels of IL-17A or IFN-γ might not be completely depleted in mice due to insufficient titers of antibodies administered in the blood infection model." (PMID 31484738, 2019).
cancer (1,421 papers, 2008 to 2026). A tumor composed of atypical neoplastic, often pleomorphic cells that invade other tissues. "Polymorphisms in the IL-17A gene have been investigated over time to find the possible association with cancers." (PMID 38816694, 2024). "IL-17A as a proinflammatory cytokine is linked to rapid malignant progression of cancer and therapy resistance." (PMID 39906741, 2024). "IL-17A expression heightens the adenoma-to-carcinoma sequence (mutational activation of cancer genes) in the intestinal epithelium of CRC patients." (PMID 37176567, 2023). "At the head of the family is IL-17A, the prototype that has been linked to the pathogenesis of immune-mediated inflammatory diseases and cancer." (PMID 35740551, 2022). "In 2014, two researchers independently performed a meta-analysis and attempted to elucidate the relationship between IL-17A rs2275913 and IL-17F rs763780 and cancer risk in Asians." (PMID 36300118, 2022). "Previous studies have demonstrated that Inflammatory cytokines such as IL-17A and IL-6 were closely linked with cancer associated inflammation." (PMID 35436305, 2022). "Accordingly, the presence of intratumoral IL-17A+ IL-23R+ IL-6+ CD4+ T cells was described to be associated with the development of colitis-associated cancer." (PMID 36428508, 2022). "Previous studies disclosed that IL-17A SNPs can affect the risk of cancer development and progression through influencing IL-17A expression in various malignancies including NSCLC." (PMID 33802737, 2021). "Authors have suggested that polymorphisms in IL17A play a critical role in certain types of cancer, and the rs3819025 has also been studied in different types of disease." (PMID 33868301, 2021). "Alongside macrophages, we have also demonstrated that IL17A significantly affects cancer-associated fibroblasts by modulating their transcriptional profile and secretome." (PMID 33802061, 2021). "Interactions between the microbiota and cells producing IL-17A have also been implicated in the pathogenesis of immune mediated inflammatory diseases and cancer." (PMID 33244315, 2020). "This is suggesting that IL-17A polymorphism is taking role in cancer susceptibility among different Sudanese ethnic groups." (PMID 32616024, 2020). "A meta-analysis study showed that IL-17A rs2275913 polymorphism is remarkably linked to the risk of many types of cancer." (PMID 31196204, 2019). "Clinical studies have detected IL-17A-producing cells in a variety of human cancer samples and increased IL-17A level is reported to associate with poor prognosis in some studies, but improved prognosis in other reports." (PMID 28562353, 2017). "Increased expression levels of IL-17A in blood and cancer tissues have been shown to be associated with the development of CAC." (PMID 28881611, 2017). "In a meta-analysis examining outcomes from all cancers types, the authors conclude that higher levels of Th17 cells are associated with a better prognosis while higher levels of IL-17A are associated with a poor prognosis." (PMID 28806403, 2017). "The aim of the present work was to clarify the effects of IL-17A G197A (rs2275913) and IL-17F T7488C (rs763780) polymorphisms on cancer risk." (PMID 26843459, 2016). "Our study represents a comprehensive meta-analysis of the role of IL-17A rs2275913 and IL-17F rs763780 polymorphisms in cancer risk." (PMID 26843459, 2016). "Odds ratios (ORs) with 95% confidence intervals (CIs) were used to assess the association of the IL-17A rs2275913G>A and IL-17F rs763780T>C polymorphisms with cancer risk." (PMID 25147431, 2014). "Many epidemiological studies have focused on the association of the IL-17A rs2275913G>A and IL-17F rs763780T>C polymorphisms with cancer risk." (PMID 25147431, 2014). "Significant associations were found between the IL-17A rs2275913G>A polymorphism and cancer risk in all five genotype models of total populations." (PMID 25147431, 2014).
cancer (continued). "In conclusion, despite these limitations, the present meta-analysis demonstrates that the IL-17A rs2275913G>A polymorphism is associated with cancer development." (PMID 25147431, 2014). "The IL-17A rs2275913G>A and IL-17F rs763780T>C polymorphisms are the most common loci associated with IL-17 activity and cancer risk." (PMID 25147431, 2014). "Recently, a subset of T-helper 17 (Th17) cells characterised by interleukin-17A (IL-17A) production was implicated as a critical mediator of inflammation and cancer." (PMID 23239971, 2012). "The IL-17A G197A allele has been associated with elevated IL-17A secretion and increased risk of cancer." (PMID 22761739, 2012). "Stratified results revealed that IL17A polymorphism was significantly associated with positive peritumor intravascular cancer emboli and high clinical stage that are associated with the survival rate of the patients." (PMID 23049595, 2012). "LCN2 is associated with UC duration and cancer risk, which may be regulated by IL-17A, IL-22, and TNF-α." (PMID 40153427, 2025). "At the same time, IL-17A secreted by cancer-associated neutrophils and cancer-associated fibroblasts (CAF) induces the expression of human antigen R (HuR) by activating the JAK2/STAT3 signaling pathway, which recognizes the mRNA encoding Snail and induces its translation." (PMID 39906741, 2024). "Additionally, recent studies have revealed that IL-17A affects the transcriptome of cancer-associated fibroblasts (CAFs)." (PMID 38835055, 2024). "Notably, mucosal tissue with microbial colonization appears to be the main cause of cancers with IL-17A overactivation." (PMID 39235230, 2024). "IL-17A has been implicated in protective γδ T cell responses in other cancer models." (PMID 37631976, 2023). "Indeed, IL-17A/F secreted by pathogenic Th17 cells has been shown to contribute to growth and metastasis of numerous cancers." (PMID 36766689, 2023). "IL-17A could activate myeloid-derived suppressor cells, recruit neutrophils, and induce the nuclear translocation of hypoxia-inducible factor-1α in cancer-associated fibroblasts to exclude CD8 + T cell infiltration." (PMID 37605139, 2023). "Moreover, the neutralization of IL-17A partly alleviated the cancer progression caused by C. albicans infection." (PMID 37067414, 2023). "Furthermore, a study found that IL-17A levels were negatively associated with clinical pain scores in cancer patients." (PMID 36248896, 2022). "IL-17A was also associated with an advanced stage of cancer." (PMID 35954312, 2022). "Current evidence presents that high expression of IL-17A is linked with the development and progression of cancers, and IL-17A could be regulated at the transcriptional level." (PMID 36300118, 2022). "More recently, IL-17A has been implicated in the regulation of CSCs in cancers." (PMID 36466926, 2022). "Recent studies suggested a pathogenic role of IL-17A in cancer." (PMID 35902909, 2022). "The tenacity of IL-17A and IL-17F exposure is suggested to increase the risk of cancer." (PMID 33924897, 2021). "However, IL-17A overproduction has been associated with chronic inflammatory disorders, autoimmune diseases and cancer." (PMID 32373132, 2020). "IL-17A, a proinflammatory factor that can induce an abnormal respiratory neutrophil response to antigen stimulation, is associated with a variety of inflammatory states, such as those in autoreactive diseases, metabolic abnormalities, and cancer." (PMID 33082827, 2020). "However, the mechanisms underlying IL‐17A‐induced up‐regulation of MMPs expression in GBMs is different from other cancers." (PMID 30353649, 2019). "Cancer-associated fibroblasts activated by chemotherapy have been shown to maintain cancer-initiating cells (CICs) and their drug resistance through secretion of IL-17A." (PMID 30513684, 2018). "IL-17A is a pro-inflammatory cytokine that contributes to the pathogenesis of inflammatory and auto-immune diseases but that also seems to be highly associated with cancer progression." (PMID 28347290, 2017).
cancer (continued). "Previous meta-analyses reported that IL-17A wasn’t significantly associated with OS in cancers." (PMID 29029520, 2017). "Recent comparison of matched patient-derived colorectal cancer samples before and after chemotherapy identified a significant increase in the secretion of IL-17A cytokine from Cancer Associated Fibroblasts (CAFs), which induced CSC properties, resulting in therapeutic resistance." (PMID 26742077, 2016). "Therefore, to clarify the role of IL-17A rs2275913 and IL-17F rs763780 polymorphisms in cancer risk, we conducted a comprehensive meta-analysis of all eligible case-control studies." (PMID 26843459, 2016). "Moreover, the category of control design did not influence the results; not only the population-based but also the hospital-based controls all showed that significant association existed between IL-17A rs2275913G>A polymorphism and cancer risk." (PMID 25147431, 2014). "Therefore, we performed a meta-analysis to clarify the possible association of the IL-17A rs2275913G>A and IL-17F rs763780T>C polymorphisms with cancer risk." (PMID 25147431, 2014). "Moreover, cancer-associated fibrosis is marked by chronic inflammation within cyto/chemokines (i.e., IL-6, IL-8, IL-17A, and IL-1α), and growth factors (i.e., SDF-1, HGF, PDGF, and TGF-β) are released by both malignant and non-cancer cells, contributing to tumor cell proliferation and invasion." (PMID 40649899, 2025). "Additionally, DNA hypermethylation can control cellular immune responses, change IL-17A genetic polymorphisms, result in extracellular instability, influence glycose metabolism and cell proliferation, and participate in the development of various cancers." (PMID 37491851, 2023). "This study highlights the need for further investigations towards addressing IL-17A and IL-17F polymorphisms among Sudanese population diagnosed with different types of cancers, in order to further understand the role of this SNP polymorphism in cancer susceptibility and further cancer incidence." (PMID 32616024, 2020). "In the IL-17 signaling pathway, increased expression of interleukin-17A is associated with poor prognosis of CRC patients, whereas blocking IL-17A inhibits CRC progression in preclinical cancer models." (PMID 41358726, 2026). "Several studies have indicated that tumors formed subcutaneously, in situ, or via the intravenous injection of cancer cell lines in mice increase IL-17A expression by γδ T cells." (PMID 40558272, 2025). "For instance, n-3 PUFAs have been shown to suppress levels of IL-6 and TNF-α in cancer patients, as well as reduce IL-17A-mediated inflammation and IL-11 expression in hepatocytes during acetaminophen-induced hepatotoxicity." (PMID 40704145, 2025). "IL-17A, a pro-inflammatory homodimeric glycoprotein composed of 155 amino acids, plays a key role in host defence, cancer progression, and inflammatory conditions." (PMID 40974979, 2025). "Interleukin 17A (IL-17A) is a pleiotropic cytokine that regulates inflammatory diseases and cancers." (PMID 40632810, 2025). "Overall, cytokines associated with effector lymphocyte cytotoxicity response (IFNg, perforin, granzyme A, granzyme B, and granulysin), cell death (FasL and TNFa), and IL-17A showed strong positive correlation with cancer cell killing (p = 0.025 to p < 0.0001)." (PMID 40589567, 2025). "IL-17A-producing γδ T cells can also re-educate neutrophils and macrophages towards an immunosuppressive and pro-angiogenic phenotype in different cancers (i.e., breast, liver, and ovarian)." (PMID 40422223, 2025). "In CRCs CAFs have a complex action by secreting IL-17A, which binds with the IL-17A receptor on cancer stem cell." (PMID 40677714, 2025). "The study underscores the clinical relevance of IL‐17A inhibition, shedding light on potential resistance mechanisms and the need for a nuanced approach in the cancer therapy." (PMID 38585232, 2024).